SPI1 (Spi-1 proto-oncogene)
Diseases named in the same sentence as SPI1 in open-access papers (continued):
Sharing a sentence is not in itself a finding about the gene and the disease.
tumor (continued). "SPI1 was strongly correlated with gene markers of CD8 + T cells, Tregs, monocytes, tumor-associated macrophages, M2 macrophages, neutrophils, dendritic cells, regulatory T cells (Tregs), and T cell exhaustion." (PMID 36477668, 2022). "SPI1 was essential for macrophage maturation and polarization, and its expression correlated with tumor grades and poor prognosis." (PMID 36430704, 2022). "We believed that SPI1 in GC can specifically recruit some immune cells to gather at the tumor site, thereby changing the proportions of infiltrating immune cells." (PMID 35237521, 2022). "The transcription factor SPI1 is an important regulatory protein that plays an extremely important role in blood cell differentiation, immune cell differentiation, as well as tumor development." (PMID 35361282, 2022). "We evaluated the methylation levels of SPI1 in the ccRCC dataset and found that tumor bulk tissues had significantly lower DNA methylation levels than the normal bulk tissues." (PMID 36477668, 2022). "To further explore the relationship between SPI1 and immunity in ccRCC, we performed a correlation analysis adjusted for tumor purity between SPI1 and gene markers of immune cells and stromal cells using the TIMER platform." (PMID 36477668, 2022). "Previous studies have found that SPI1 acts as a tumor suppressor by regulating cell cycle and apoptosis in classical Hodgkin’s lymphoma cells." (PMID 35237521, 2022). "Immunohistochemical staining revealed increase of Ly6G+ neutrophils within xenograft tumours and metastatic lungs formed by LoVo cells stably over‐expressing SPI1." (PMID 34841706, 2021). "Since above results revealed abundance of SPI1 in tumour stroma, and considering its roles as a master regulator of neutrophil differentiation, we further investigated the impact of neutrophils on aerobic glycolysis and cancer progression." (PMID 34841706, 2021). "Our results show that NCFs and their coexpressed genes, including SPI1, HCK, VAV1, CD53, and ITGB2, are significantly associated with tumor-infiltrating immune cells, especially with immunosuppressive macrophages." (PMID 34708124, 2021). "Our results suggested that the transcription activity of SPI1 is essential for macrophages and microglia maturation and polarization, leading to a tumor-harmful microenvironment formation." (PMID 34434898, 2021). "During an observation period of 12 months, 50% of Spi-1 transgenic mice developed hepatosplenomegaly with extensive erythroblast infiltration and occasional tumor cells on the peripheral blood smears." (PMID 33898929, 2021). "We found that the elevated expression level of SPI1 had lower tumor purity and a higher infiltrating level of macrophage (Tumor purity: r = −0.528; macrophage infiltration: r = 0.687), so did TAM genes." (PMID 34434898, 2021). "More specifically, the tumor suppressor AGTR1 was found to be increased in 5 of the 7 tumor samples, while the tumor suppressor SPI1 was found to be increased in 4 samples." (PMID 28178311, 2017). "More specifically, the AGTR1 and SPI1 genes were identified as showing copy number increases in 5 and 4 samples, respectively, whereas the expression of these tumor suppressors was downregulated in the LUSC dataset." (PMID 28178311, 2017). "To test if Salmonella invasion of any cell type is required for the use of eutC in the tumor tissue, we generated a strain carrying deletions of invA and ssaD, which encode structural components of the T3SS encoded in SPI-1 and SPI-2, respectively." (PMID 27145267, 2016). "As a first indication, transcription of the fli-1 gene is directly regulated by Spi-1 in Friend tumor cells." (PMID 18983647, 2008).
tumor (continued). "During DMSO-induced erythroid differentiation of Friend tumor cells, it was noticed that one of the early events was a marked decline in the level of Spi-1 expression." (PMID 18983647, 2008). "Overall, the available data indicate a stage- and grade-dependent regulation of SPI1 in the tumor microenvironment, which could correlate with the immunological status and progression of the tumor disease." (PMID 40895524, 2025). "Although public RNA-seq datasets (e.g., TCGA) show reduced SPI1 expression in NSCLC tumor tissue compared to normal tissue, these data represent bulk transcriptomes and may not reflect immune-cell–specific protein expression and function." (PMID 40895524, 2025). "In the mouse model, there are conflicting reports as to whether SPI-1 or SPI-2 virulence genes are required for tumor invasion." (PMID 39873483, 2025). "Moreover, interleukin 8 (IL8) and interleukin 10 (IL10) produced by TAMs promote ITGβ8 transcription in tumor cells through spi‐1 protooncogene (SPI1)." (PMID 39535362, 2025). "We then investigated whether tumor colonization and intracellular invasion or replication required SPI-1 or SPI-2 in the CAM tumor model." (PMID 39873483, 2025). "In cancer biology, SPI1 contributes to tumor progression across various contexts." (PMID 41299786, 2025). "The increased expression of SPI1 (PU.1) in the peritumoral and tumor region in patients with early tumor stages could indicate an active immune response at the early to intermediate course of the tumor disease." (PMID 40895524, 2025). "TFs like PAX5 and SPI1 might regulate the immune cell composition in the tumor, including myeloid cell recruitment." (PMID 41238550, 2025). "Indeed, JUNB and JUNA are found critical downstream effectors of the tumor suppressor activity of another ETS gene family SPI1/PU.1, and that reduced expression of JUNB shown to be a common feature of acute myeloid leukemogenesis." (PMID 38461240, 2024). "Moreover, recent studies have shown that SPI1 can enhance the activity of tumor stem cell mesenchyme by regulating the PI3K/Akt signaling pathway, thereby promoting cancer development." (PMID 39491527, 2024). "Therefore, investigating the function of SPI1 in glycolysis is helpful for developing promising tumour therapeutic targets." (PMID 37539493, 2023). "Interestingly, hypoxia, an important tumor microenvironmental stimulus, increased the expression of both SPI1 and ACAP1 in Jurkat cells." (PMID 36497434, 2022). "SPI1 expression was positively and strongly associated with T cell exhaustion markers (LAG3 and PDCD1,), and Treg cell markers (FOXP3 and CCR8), suggesting that high SPI1 expression level inhibits anti-tumor immunity." (PMID 36477668, 2022). "The TME with high SPI1 expression level can simultaneously maintain high CD68 + macrophages, implying that SPI1 may be located in M2 macrophages and contributes to tumor-associated macrophage-mediated cancer progression." (PMID 36477668, 2022). "Based on the role of interleukin-1β (IL-1β) in modulating the tumor microenvironment and further promoting tumor growth, the SPI1-IRF coactivating complexes might play a role in contributing to the formation of an inflammatory tumor microenvironment." (PMID 35664436, 2022). "In conclusion, our results indicate that SPI1 is a tumor promoting gene." (PMID 35361282, 2022). "If dysregulated, SPI1 can function as a tumor suppressor or as oncogene." (PMID 29439554, 2018). "Recent studies reported that the oncogene SPI1 is involved in tumor progression and metastasis." (PMID 25943543, 2015).
tumor (continued). "SPI1 is a member of the E26 transformation-specific transcription factor family, which not only regulates the differentiation of myeloid cells and B cells but also plays a crucial role in tumour immune evasion, particularly by regulating PD-L1 expression to promote CD8+ T cell exhaustion." (PMID 40299520, 2025). "Notably, SPI1 expression was even further elevated in the tumor region, suggesting that PU.1 may also play a key role in the immunological or pathological processes within lung tumors." (PMID 40895524, 2025). "In addition, although current studies have obtained useful findings, more laboratory studies both in vitro and in vivo are needed to validate these bioinformatic results in the future, such as the levels of SPI1-TYROBP-FCER1G network-regulated immune molecules in OS tumor cells." (PMID 35078433, 2022). "Furthermore, SPI1 participates in tumor progression by playing a transcriptional regulatory role." (PMID 35771155, 2022). "SPI1 might promote tumor progression via regulating immune infiltration and the cell cycle of GC." (PMID 35237521, 2022). "APMAP was mainly expressed in lymphocytes and cancer cell, SPI1 was highly expressed in macrophages, and ADAM10 showed high expression in cancer cell and lymphocytes, indicating their potential roles in tumor immunity and microenvironment regulation." (PMID 40396172, 2025). "Epigenetic modifications such as methylation of the TME can impact genes like beta-2-microglobulin (β2M) and Spi-1-proto-oncogene (SPI1), which control CD1D expression that is crucial for tumor antigen presentation and immune recognition." (PMID 40872475, 2025). "First, we determined that ChromVAR‐inferred binding of transcription factors important for driving myeloid cell development (such as SPI1 and CEBPA) were more significantly more prevalent in tumour than benign pancreata." (PMID 38426634, 2024). "The expression of SPI1 was normalized to GAPDH, and results were presented as fold-change in tumor tissues relative to matched adjacent normal tissues." (PMID 35361282, 2022). "We confirmed the restriction of SOX2 expression to tumor cells, PTPRC/CD45 to immune cells, SPI1/PU.1, CD68, and CD163 to ‘macrophages’, CD3G to ‘T cells’, and OLIG1/2 and MBP to oligodendrocytes." (PMID 35973991, 2022). "Collectively, a LINC01094/SPI1/CCL7 axis was defined in LUAD, which is potentially linking to macrophage infiltration and tumor development." (PMID 36118415, 2022). "Meanwhile, the roles of SPI1 and SPIB in glucose metabolism reprogramming or reciprocal interplay of malignant tumour cells with microenvironment still remains elusive." (PMID 34841706, 2021). "Our results reveal that SPI1 and SPIB exert tumour‐promoting functions driving glycolytic process and progression of cancer." (PMID 34841706, 2021). "For validation, qRT-PCR of an ESCC patient cDNA microarray was performed, and demonstrated that C1QA, C3AR1, LCP2, SPI1, and TYROBP were up-regulated in tumor samples and predict poor prognosis." (PMID 34926275, 2021). "The E26-transformation-specific (ETS) transcription factors PU.1 (SPI1) and Spi-B (SPIB) are important tumour suppressor genes that regulate B cell development and function." (PMID 34679751, 2021). "The levels of eight genes (SPI1, RNASE6, C1QB, C1QC, CSF1R, C1QA, TBC1D2, and ATP6V0E1) expression were higher in tumor samples from UALCAN." (PMID 32038997, 2019). "We further show that SPI1 and the STAT family are the top ranked modulators of this immune gene signature, representing key regulatory nodes of tumor immune response in human cancers." (PMID 30956779, 2019). "It has been previously demonstrated that the TP63/TP53L, ERG, GRHL1/Get-, HNF1A/TCF-1, SPI1/PU.1, WT1 and GLIS2, FOXM1 and FOXP3 transcription factor networks, which are mediated by HNF4A, can regulate the expression of Trop2 in tumor tissues." (PMID 25779928, 2015).
tumor (continued). "Other anti-apoptotic genes, such SPI-1 and SPI-2, have also been shown to enable preferential viral replication selectively in tumor tissues, allowing for more targeted therapy." (PMID 23506710, 2013). "Recently, the critical hematopoietic-specific transcription factor PU.1 (also known as SPI-1), which is located within this region, is proposed as a ML tumor suppressor." (PMID 18922187, 2008). "Tumor bulk RNA-Seq data highlighted that the tumor expression of 5/32 genes (IRF1, IKZF1, SPI1, SH2B3, LAT) was each strongly correlated (Spearman’s ρ > 0.5) with at least one intra-tumor T/myeloid cell infiltration marker (CD4, CD8A, CD11B, CD45) in every one of the cancer types." (PMID 40428397, 2025). "SCRIPro could accurately predicts well-known master regulators including SPI1, IRF1, FLI1, and STAT2 for mono/macrophages, GATA3, RUNX3, SMARCA4, JUND, and MYB for T-cells, PAX5, BCL2, and IRF4 for B and tumor B-cells." (PMID 39024032, 2024). "Further, we employed SCENIC to predict transcription patterns of tumor cells, finding a series of key TFs of HCC tumorigenesis, such as TFs in regulation of cell dedifferentiation (SPI1, HMGB3, and YBX1) and in abnormal bile acid metabolism (NR1H4, NR1I3, FOXA3 and DDIT3)." (PMID 37985711, 2023). "Moreover, the tumor specimens were all stained by immunohistochemistry to show the expression of DGCR8, SPI1, TNF-α, nestin, and Ki-67." (PMID 35945192, 2022). "SPI1 expression was detected in 16 pairs of fresh tumor tissues and adjacent nontumor tissues by western blot and quantitative real-time PCR (qRT-PCR)." (PMID 35237521, 2022). "Additionally, the analysis showed that C1QA, C3AR1, LCP2, SPI1, and TYROBP were up-regulated in tumours with the worst prognosis." (PMID 35743646, 2022). "Collectively, this research suggests that LINC01094 binds to SPI1 to promote its nuclear translocation, which further activates CCL7 transcription by binding to its promoter, leading to M2 macrophage accumulation and dissemination of tumor cells." (PMID 36118415, 2022). "Unlike SPI1, a tumor suppressor and being lowly expressed in AML, we demonstrate that circSPI1 acts as an oncogene, evidenced by the observation that circSPI1 knockdown induces myeloid differentiation and apoptosis of AML cells." (PMID 33741901, 2021). "Through physical interaction with co‐factor SPIB, SPI1 exerted tumour‐promoting functions in glycolytic process and progression of cancer, shedding light on the SPIB/SPI1‐mediated positive interplay loop of cancer cells and neutrophils as a therapeutic target against cancers." (PMID 34841706, 2021). "Hence, this finding corroborated that the loss of SPI-1 and SPI-2 genes did not impair the tumor-colonizing ability of STm, because STm was predominantly extracellular on the CAM tumors." (PMID 39873483, 2025). "Although SPI-1-mediated tumor invasion and SPI-2-associated intra-tumoral replication were reported to be important, in the majority of mouse tumor studies, virulence functions were not required, as bacteria were extracellular on tumor sites." (PMID 39873483, 2025). "SPI1 staining was mainly observed in TIICs rather than in tumor cells." (PMID 36477668, 2022). "Taken together, we opine that LINC01094 binds to SPI1 and promotes its nuclear translocation, which therefore binds to CCL7 promoter and activates its transcription, leading to increased chemotaxis and M2 skewing of macrophages in LUAD and aggravated tumor progression." (PMID 36118415, 2022).
tumor (continued). "While overexpression of MIR503HG in tumor tissues did not alter the protein level of SPI1." (PMID 35771155, 2022). "SPI1 was more highly expressed in tumor-infiltrating immune cells rather than in cancer cells." (PMID 36477668, 2022). "However, circKPNB1 knockdown resulted in smaller tumor volumes than the negative control, and this inhibiting effect was also reversed after SPI1 overexpression." (PMID 35945192, 2022). "According to the results of IHC staining, SPI1 was mainly expressed in the cell nuclei of immune cells, rather than in tumor cells, implying that SPI may be a biomarker of immune cells infiltration in TME." (PMID 36477668, 2022). "Furthermore, the concept that Spi-1 could inhibit the function of GATA-1 in erythroleukemic cells is supported by the reversal of tumorigenicity and the re-initiation of a differentiation program when GATA-1 expression is ectopically imposed in a Friend tumor cell line." (PMID 18983647, 2008). "Similarly, treatment with LoVo cells with EVs secreted by mouse xenograft tumours‐isolated TANs, but not with those from murine PNs, elevated the expression levels of HK2 and PGK1, while silencing of Spi1 in TANs prevented these changes." (PMID 34841706, 2021).